HMGB1 (high mobility group box 1)
Diseases named in the same sentence as HMGB1 in open-access papers (continued):
Sharing a sentence is not in itself a finding about the gene and the disease.
neurological disorders (35 papers, 2012 to 2025). "As an endogenous damage-associated molecular pattern (DAMP), HMGB1 contributes to inflammation and the innate immune response in various neurological diseases." (PMID 37528661, 2023). "Accumulating evidence has shown that HMGB1, as a key promoter of neuroinflammation, is believed to be involved in the neurodegenerative process of various neurological disorders, including PD." (PMID 38172670, 2024). "Since neuroinflammation plays an important role in neurological disorders, we focused on the HMGB1–RAGE axis." (PMID 37109411, 2023). "Some studies have found that HMGB1 is involved in the development of several cognitive-emotional disorders and neurological diseases." (PMID 36860860, 2023). "HMGB1 can cause BBB breakdown and aggravate neuroinflammation and oxidative stress in neurological diseases." (PMID 36311523, 2022). "The preclinical and clinical evidence discussed here reinforces HMGB1 as a promising candidate as a common biomarker and therapeutic target for neurological disorders in which neuroinflammatory pathways play a central role." (PMID 36388178, 2022). "Hence, HMGB1 is now a potential target during the treatment of various neurological diseases and the outcomes in this study will provide further theoretical support." (PMID 36483598, 2022). "Additionally, some research has suggested that the levels of BDNF may be subject to regulation by HMGB1, particularly in neurological disorders and inflammatory processes." (PMID 38982490, 2024). "Thus, under conditions of stress, glucocorticoids induce astrocytic HMGB1 release, leading to a neuroinflammatory state that could mediate neurological disorders such as MDD." (PMID 32344830, 2020). "HMGB1/TLR4 signaling activation exacerbates neuroinflammatory responses and is involved in the pathogenesis of various neurological diseases, so HMGB1 is regarded as a key alarmin molecule connecting innate immunity and neuroinflammation." (PMID 41155637, 2025). "High-mobility group box 1 (HMGB1) is a mediator of early response, and as a damage-related protein mediates neuroinflammation and brain injury in a variety of neurological diseases." (PMID 36577981, 2022). "DNA-binding protein high-mobility group box 1 (HMGB1) is released as a result of cell damage or death into the extracellular environment and has the capability of stimulating TLR4 in many neurological disorders with an inflammatory component." (PMID 35216110, 2022). "Recent studies have shown that SIRT1 activation can reduce the secretion of high-mobility group box 1 (HMGB1) and moderate the subsequent HMGB1/TLR4/MyD88/NF-κB signaling pathway to exert protective and anti-inflammatory effects against neurological disorders." (PMID 33981300, 2021). "In addition, HMGB1 may be a helpful candidate biomarker to differentiate TBM from TB in earlier stages, predict disease prognosis, or at least confirm neurological disorders in confirmed cases of TBM." (PMID 27795917, 2016).
infectious disease (29 papers, 2010 to 2025). A disorder directly resulting from the presence and activity of a microbial, viral, or parasitic agent in humans. "High-mobility group box 1 (HMGB1), a member of damage-associated molecular patterns (DAMPs), is involved in the immune regulation of several infectious diseases." (PMID 36139393, 2022). "Many studies have reported that HMGB1, as an important late-stage inflammatory mediator, is an important therapeutic target for infectious diseases such as sepsis-associated encephalopathy and autoimmune encephalomyelitis at an early stage." (PMID 34539383, 2021). "Therefore, extracellular HMGB1 is associated with both inflammatory and repair responses in infectious diseases, trauma, and autoimmune disorders." (PMID 37628850, 2023). "We anticipate that this novel strategy will apply to the treatment of multiple infectious and non-infectious diseases in which HMGB1-mediated TLR4 signaling is a central driver of inflammation." (PMID 39699172, 2025). "High mobility group box 1 protein (HMGB1), a lethal late inflammatory mediator, contributes to the pathogenesis of diverse inflammatory and infectious diseases." (PMID 37403077, 2023). "TNF-α, IL-1β, and HMGB1 (high mobility group box 1) are pro-inflammatory factors present in the process of many infectious diseases." (PMID 34834206, 2021). "High mobility group box 1 (HMGB1), an established mediator in both infectious disease and sterile injury, is abundantly expressed in neurons." (PMID 33353552, 2020). "Mechanistic knowledge of the secretory route taken by HMGB1 would open the door for therapeutic manipulation of HMGB1 release, with clear implications for inflammatory and infectious diseases." (PMID 32917873, 2020). "HMGB1 is an actively secreted cytokine produced by macrophages and other inflammatory cells that participates in various infectious diseases." (PMID 30157804, 2018). "However, in the literature the role of HMGB1 in inflammatory and infectious diseases was described before in different settings." (PMID 34671818, 2022). "Resembling the work using anti-HMGB1 antibodies, animal studies revealed that HMGB1 Box A treatment prevented the proinflammatory cytokine effects of HMGB1 and improved both infectious and non-infectious diseases." (PMID 34684184, 2021). "The strong correlation between HMGB1 and the pathogenesis of various infectious diseases suggests that it may provide an optimum target for treatment and clinical use." (PMID 29064403, 2017). "HMGB1 is a nuclear component, but extracellularly, it serves as a signaling molecule involved in the pathogenesis of Pseudomonas keratitis, as well as other infectious diseases." (PMID 29064403, 2017).
immune disorders (28 papers, 2015 to 2025). "Conclusions: cFLCs and HMGB1 reflect the inflammation and immune dysfunction in HD patients representing two strong and independent risk markers of mortality." (PMID 36498479, 2022). "HMGB1-induced immune disorder provokes inflammatory storms causing cell and organ damage via the TLR2/4-NF-κB signaling pathway." (PMID 36139393, 2022). "The release of Damage-Associated Molecular Patterns (DAMPs), such as HMGB1, and cytokines (e.g. IL-1β) creates an environment of immune dysfunction often leading to end organ failure and death." (PMID 29601597, 2018). "Moreover, the higher clearance rate of DAMPs, especially HSP70 and HMGB1, was significantly associated with immune disorders and poor prognosis." (PMID 30666251, 2018). "SLC25A37 and SLC25A28 increase mitochondrial iron accumulation, leading to the upregulation of PD-L1 through the HIF-1α/AIM2/high mobility group box 1 (HMGB1) axis, resulting in immune dysfunction." (PMID 41373022, 2025). "In this study, we investigated the mechanism of HMGB1 release during MG infection and its role in triggering immune disorders." (PMID 36139393, 2022). "We previously identified HMGB1 as a potential drug-target in caspase-11-mediated lethal immune disorders, such as sepsis." (PMID 33854044, 2021). "We now find HMGB1/IL-1β complexes in human and mouse plasma, and identify a synergistic role of HMGB1/IL-1β complexes in post-burn immune dysfunction." (PMID 29601597, 2018). "HMGB1, plays a key role as an immune modulating factor and its potential role in cell mediated immune dysfunctions ought to be investigated further." (PMID 28628607, 2017). "The precise mechanisms for protective effects of anti-HMGB1 mAb on trauma-induced immune dysfunction in the spleen remain to be established." (PMID 25709155, 2015). "Therefore,HMGB1 plays a role in the course of immune system diseases, diagnosis anddetermination of disease prognosis." (PMID 41209506, 2025). "It is known that HMGB1 is effective in the diagnosis and prognosis of immune system diseases." (PMID 41209506, 2025). "Our group found that in the absence of TLR2, MG could induce inflammation via TLR6 in DF-1 cells, or TLR4 could be activated by HMGB1 to trigger MG-induced immune disorders in avian macrophage cells." (PMID 37238096, 2023). "In addition, our results showed that TLR2/4 activated by HMGB1 further activates the NF-κB pathway to produce immune disorders." (PMID 36139393, 2022). "High-mobility group box-1 (HMGB1) protein is passively released from necrotic cells and actively secreted by inflammatory cells, and is implicated in the pathogenesis of various inflammatory and immune diseases." (PMID 36497194, 2022). "However, the alleviation of immune disorders by knocking down TLR2 or TLR4 alone remained unimpressive due to the HMGB1 preferential recognition effect of TLR2 and the compensation effect of TLR4." (PMID 36139393, 2022). "More importantly, TLR4 could be activated by HMGB1 to trigger immune disorders after TLR2 was silenced." (PMID 36139393, 2022). "However, secretory HMGB1 exerts excessive activation of immune cells, induces overexpression of pro-inflammatory cytokines, and triggers immune disorders." (PMID 36139393, 2022). "High-mobility group protein B1 (HMGB1) is one of the most abundant non-histone nuclear proteins that can serve as an alarmin or damage-associated molecular pattern (DAMP) to drive the pathophysiological processes of inflammatory and immune diseases." (PMID 38347600, 2024). "Furthermore, recently investigated biomarkers of mortality, such as free light chains (FLCs) or serum high mobility group box 1 (HMGB1), may serve as important parameters that reflect inflammation and immune dysfunction in CKD and AKI patients." (PMID 37241006, 2023).
immune disorders (continued). "Interestingly, high-molecular weight and denaturing-resistant HMGB1 complexes, rising from protein-cross-linking activity of TG2 enzyme, have been observed in the plasma and PBMC of individuals with immune disorders and, to a much lesser extent, in healthy subjects." (PMID 30453584, 2018).
kidney (26 papers, 2014 to 2025). "The inflammatory initiators or propagators have been actively investigated and recent studies have identified the damage-associated molecular pattern HMGB1, as one of the initiators during IR, propagating inflammatory signaling and exacerbating kidney damage after an ischemic insult." (PMID 31072024, 2019). "With this in mind, our aim was to characterise the role of the protein High Mobility Group Box 1 (HMGB1) in colorectal neoplastic progression." (PMID 36980751, 2023). "As to liver IRI, damage-associated molecular patterns (DAMPs) such as high-mobility group box 1 (HMGB-1) proteins, free fatty acids, and heat shock proteins are released from damaged liver sinusoidal endothelial cells and hepatocytes." (PMID 35572528, 2022). "HMGB-1 has been reported as one of the DAMPs released from necrotic cells and hepatocytes in the case of liver IR insult, which leads to the activation of macrophages, followed by the production of proinflammatory cytokines." (PMID 35572528, 2022). "We have previously demonstrated that macrophage produced-HMGB1 (high mobility group box 1) can activate RAGE (receptor for advanced glycation end-products) on iNKT cells to amplify IL-17 production to mediate lung IR injury." (PMID 29268735, 2017). "We also found that both glycyrrhizin-mediated inhibition of HMGB1 and intracerebroventricular neutralizing antibody treatments before middle cerebral artery occlusion onset diminish infarct volume." (PMID 27544687, 2016). "Therefore, we showed that H. hepaticus–induced liver preneoplasia is closely correlated with the activation and accumulation of HMGB1." (PMID 35046917, 2021). "Furthermore, these protective effects of RIPC against liver IR injury appear to be mediated by KATP through inhibiting HMGB1-induced TLR4/MyD88/NF-κB signaling." (PMID 31771292, 2019). "Furthermore, the increased HSP70 and HMGB1 protein levels were predominantly located in the tubules of the diabetic kidney." (PMID 26398934, 2015). "Subsequently, in the lung IRI mouse model and HR cell model, our findings demonstrated that the release of HMGB1 from endothelial cells undergoing ferroptosis facilitated NET formation through activation of the TLR4-MYD88 pathway." (PMID 39268501, 2024). "Effects of liver IR combined with intraperitoneal administration of aucubin (1, 5, and 10 mg/kg for 10 days) on serum TNF-α, IL-1β, and HMGB1 levels in experimental rats." (PMID 33013386, 2020). "In conclusion, our results verify the reno-protective potential of AEA against HgCl2-induced kidney injury by its anti-inflammatory, antioxidant, and anti-apoptotic capacities by modulating WNT-5A/BCL-2, IP3/NFATC1, HMGB-1/RAGE/NF-κB, caspase-1/IL-18, and caspase-3/BCL-2 cues." (PMID 37488162, 2023). "During liver IR, ROS promote expression of the early response transcription factor IRF-1, enhance activity of histone acetyl transferase, and promotes acetylation of HMGB1." (PMID 33013386, 2020).
metabolic disorders (23 papers, 2013 to 2026). "PRRs can also be triggered by the production of other endogenous damage-associated signals during the development of metabolic diseases, such as high mobility group box 1 (HMGB1) and fetuin A." (PMID 31582899, 2019). "While HMGB1 is a well-known marker of inflammation, increased expression of HMGB1, associated with its promoter DNA’s methylation alteration, was reported in cardiac progenitor cells following hypoxia and metabolic diseases, suggesting that DNA methylation is a mechanism for HMGB1 regulation." (PMID 37107654, 2023). "Dysfunctional mitochondrial autophagy involving HMGB1 is associated with metabolic diseases." (PMID 37065747, 2023). "Importantly, cardiomyocyte-specific HMGB1 deletion causes metabolic disorder in the myocardium." (PMID 35281739, 2022). "As HMGB1 plays important roles in metabolic diseases, significant efforts have been directed towards the discovery of specific HMGB1 inhibitors." (PMID 35706377, 2022). "Taken together, extracellular HMGB1 is involved in the development of metabolic diseases, mainly through its cytokine‐like effects." (PMID 35706377, 2022). "As autophagy is a process underlying many human diseases, it would be interesting to further study the roles of HMGB1 on autophagy in metabolic diseases." (PMID 35706377, 2022). "Herein, we summarize the literature reports on the roles of HMGB1 in metabolic diseases and discuss the perspectives of targeting HMGB1 as a potential therapeutic approach." (PMID 35706377, 2022). "This review also discusses the feasibility of targeting HMGB1 as a potential pharmacological intervention for metabolic diseases." (PMID 35706377, 2022). "The current review examines the up‐to‐date findings pertaining to the biological functions of HMGB1, with focus on its posttranslational modifications and roles in downstream signalling pathways involved in metabolic diseases." (PMID 35706377, 2022). "Based on these findings, we chose to treat PBMCs with HMGB1 in combination with IL-2 to reproduce a microenvironment similar to the inflammatory-related conditions potentially present in metabolic diseases such as T2DM." (PMID 34360753, 2021). "Therefore, the current review will focus on the role of HMGB1 in metabolic diseases, given the fact that inflammation also plays a critical in the initiation, propagation and development of metabolic diseases." (PMID 35706377, 2022). "Previously, the functions of extracellular HMGB1 in metabolic diseases have been widely studied." (PMID 35706377, 2022). "High-Mobility Group Box 1, a well-known damage associated molecular pattern (DAMP), is a highly conserved non-histone nuclear protein that is known to play pivotal roles in the pathogenesis of metabolic diseases and related chronic inflammation." (PMID 31507457, 2019). "Second, HMGB-1 can activate the nuclear factor-κB (NF-κB) in metabolic disease." (PMID 27738641, 2016). "Thus, targeting extracellular HMGB1 might provide potential therapeutic agents for metabolic diseases." (PMID 35706377, 2022).
heart disease (14 papers, 2011 to 2026). "In the heart, the TLR4/HMGB1 pathway has been demonstrated to mediate inflammatory and injurious responses associated with heart diseases, in particular regulating the apoptotic death of cardiomyocytes." (PMID 35053332, 2022). "Finally, higher levels of circulating HMGB1 are associated to human heart diseases." (PMID 30306212, 2019). "We evaluated and synthesised available evidence regarding the molecular functions as well as the clinical and therapeutic utility of HMGB1 in heart disease." (PMID 41957310, 2026). "Several studies demonstrated an involvement of HMGB1 in modulating macrophage polarization toward both phenotypes in different cardiac diseases." (PMID 35053332, 2022). "In heart diseases, the role of HMGB1 is very controversial; studies have suggested that it is a marker of myocardial damage, whereas it also plays a role in tissue repair and regeneration." (PMID 32850832, 2020). "In addition, HMGB1, a highly conserved DNA binding protein, also plays a variety of roles in heart disease according to its cellular localization." (PMID 34859077, 2021). "Recent reports have shown the involvement of a variety of miRNAs in cardiac disease and, specifically, in cardiac remodelling and fibrosis, however, under our experimental conditions HMGB1 did not modulate these miRNA." (PMID 21731608, 2011).